IRS1 (insulin receptor substrate 1)
Diseases named in the same sentence as IRS1 in open-access papers (continued):
Sharing a sentence is not in itself a finding about the gene and the disease.
Insulin resistance (continued). "By contrast, the specific serine phosphorylation of the IRS-1/2 by the c-Jun N-terminal kinase (JNK1) and other protein kinases inhibits insulin-stimulated tyrosine phosphorylation, which correlates closely with insulin resistance." (PMID 25346723, 2014). "Furthermore, TNFα has been suggested to be involved in inducing insulin resistance in adipocytes, and retinal endothelial cells (REC) through activation of insulin receptor substrate 1 (IRS-1)Ser307 and stimulation of apoptosis." (PMID 25073020, 2014). "Mice lacking IRS-1, although showed mild insulin resistance when young, not only lived longer but also maintained better glucose homoeostasis compared to wild-type controls at older ages." (PMID 24474199, 2014). "Diet-induced over-activation of mTORC1 in muscle has been shown to inhibit insulin signaling via a feedback mechanism involving S6K-mediated serine phosphorylation of IRS-1, which reduces the ability of IRS1 to activate PI3K, leading to impaired glucose uptake and systemic insulin resistance." (PMID 24740400, 2014). "Impairment of insulin receptor substrate-1 (IRS-1) by HCV core protein directly or through a variety of cytokines and trace elements may account for insulin resistance in those patients." (PMID 24016701, 2013). "The mechanism whereby excessive FFAs in the blood induce insulin resistance is partly through the mediation of protein kinase C, resulting in impaired function of insulin receptor substrate-1 (IRS-1), which further activates JNK and SOCS3, contributing to insulin resistance." (PMID 22278044, 2013). "For example, mTOR is involved in the development of insulin resistance via a negative feedback loop, i.e. the inhibition of IRS-1 tyrosine phosphorylation, while the inhibitory effect of curcumin on mTOR has been demonstrated in certain cancer cells." (PMID 22253696, 2012). "In this study, we demonstrated that ARA extract can increase the phosphorylation of IRS-1 and PI3K and the expression of GLUT4 in adipocytes, suggesting that ARA extract may improve insulin resistance." (PMID 22978376, 2012). "Based on other reports, it was indicated that HCV infection may also impair the insulin-induced IRS-1, PI3K and Akt phosphorylation that lead to insulin resistance." (PMID 22721429, 2012). "We found no significant change in p-Ser321 IRS-1 or in p-AKT levels in RA patients with either low or high baseline insulin resistance." (PMID 22691241, 2012). "Both IL-6 and TNF may inhibit the transcription of IRS-1 and glucose transporter (GLUT)-4 genes, thus reducing glucose transport and enhancing insulin resistance in obese patients." (PMID 22691241, 2012). "In particular, we found that ectopic expression of miR-126, an induced IRS-1-targeting miRNAs, represses translation of IRS-1 without altering the mRNA level of IRS-1, which subsequently leads to insulin resistance in hepatocytes." (PMID 21464990, 2011). "Furthermore, we found that mitochondrial dysfunction induced the expression of several miRNAs thought to target the IRS-1 3′UTR and that miR-126 was actively involved in the development of insulin resistance." (PMID 21464990, 2011). "Activation of JNK has been established as a stress-mediated inducer of insulin resistance in diabetic animal models via phosphorylation of IRS-1 at Ser-307, leading to inactivation of IRS-1 by interfering with the interaction of the insulin receptor and IRS-1 and promoting IRS-1 degradation." (PMID 21119656, 2011). "Also of note we found a normalization of local markers of insulin resistance in adipose tissue, such as SOCS3 and IRS1." (PMID 20543949, 2010). "The importance of IRS1 in insulin signalling is supported by the fact that decreased levels of IRS proteins, coupled with decreased levels of the IR itself, contribute to the insulin resistance in diabetic states in both rodents and humans." (PMID 19308256, 2009).
Insulin resistance (continued). "However, the expression of insulin signal proteins (IRS1 and GLUT4) was inhibited in SBRs, which is why prednisolone produces insulin resistance." (PMID 19646276, 2009). "Further, while a reduction in tyrosine phosphorylation in IRS-1 per se does not reduce IRS-1 content, it will result in insulin resistance in skeletal muscle." (PMID 16729893, 2006). "However, excessive FAO could inhibit IRS1 tyrosine phosphorylation and attenuate PI3K/Akt signaling, establishing a self-reinforcing cycle of insulin resistance." (PMID 40747301, 2025). "The results indicate that IRS1 or IRS2 may facilitate insulin action in the liver, thereby maintaining systemic glucose tolerance, particularly when β-cell function is able to offset insulin resistance." (PMID 40747301, 2025). "Additionally, GABA activates the PI3K/AKT pathway (phosphoinositide 3-kinase/protein kinase B), enhancing the expression of insulin receptor substrate 1 (IRS1) and GLUT4, thereby boosting insulin sensitivity and reducing homeostatic model assessment for insulin resistance (HOMA-IR)." (PMID 41003010, 2025). "Mechanistically, AβOs may induce or exacerbate neuronal insulin resistance through the aberrant activation of the TNF-α/JNK (tumor necrosis factor α/c-Jun N-terminal kinase) pathway, leading to serine phosphorylation of IRS-1 and inducing mitochondrial oxidative stress." (PMID 39966707, 2025). "The major mechanisms of insulin resistance in CKD are thought to involve pro-inflammatory cytokines such as tumor necrosis factor-α (TNF-α), interleukin-6 (IL-6), and interferon-γ (IFN-γ), which inhibit phosphorylation of the insulin receptor and insulin receptor substrate-1 (IRS-1)." (PMID 41157262, 2025). "Boys showed positive correlations between placental IRS1 expression and parameters related to body composition (weight-SDS, hip circumference, LBM, and visceral fat), while girls exhibited positive correlations with markers of insulin resistance (insulin and HOMA-IR) (all p ≤ 0.05)." (PMID 40243885, 2025). "However, in insulin resistance, reduced IRS-1/PI3K-Akt signaling fails to inhibit FOXO1, leading to excessive expression of phosphoenolpyruvate carboxykinase (PEPCK) and glucose-6-phosphatase (G6Pase), which drive hepatic glucose overproduction." (PMID 41235339, 2025). "In AD and obesity, brain insulin resistance denotes reduced neuronal and glial responsiveness to insulin, characterized by impaired IRS-1/PI3K-AKT signaling, increased inhibitory serine phosphorylation of IRS-1, and downstream overactivation of GSK3β that favors tau phosphorylation." (PMID 41155642, 2025). "Corosolic acid exerts its antidiabetic effects by regulating insulin receptor substrate-1 (IRS-1), protein kinase B (Akt), and liver kinase B1 (LkB1), thereby mitigating adenosine monophosphate-activated protein kinase (AMPK) activation to alleviate insulin resistance." (PMID 40143139, 2025). "Indeed, any factors that reduce IRS-1 phosphorylation or induce serine IRS-1 phosphorylation at the 307 site by some kinases, such as IKKβ/NF-κB and c-Jun N-terminal kinase (JNK), would impair insulin signal transduction and lead to insulin resistance." (PMID 38952394, 2024). "Hence, impaired IRS-1 activity causes metabolic complications; for example, mice without IRS-1 (IRS-1-KO mice) exhibit insulin resistance." (PMID 38988671, 2024). "Mice lacking IRS1 or IRS2 exhibited peripheral insulin resistance." (PMID 38494853, 2024). "Brain insulin resistance that depends on IRS-1 dysfunction may promote cognitive decline, independent of the classic Alzheimer’s disease pathology." (PMID 38397072, 2024). "In addition to phosphorylating IRS-1, JNK contributes to insulin resistance through promoting metabolic inflammation and negatively regulating interactions between PPARα-FGF21 as well as contributing to adiposity through dysregulation of the thyroid-stimulating hormone (TSH) axis." (PMID 38257161, 2024).
Insulin resistance (continued). "Specifically, there were quantitative differences between the expressions of IRS1, PIK3R1, SLC2A1, SLC2A3, and SLC2A4 among the patients with GDM during pregnancy and at 1-year postpartum, i.e., in the two studied groups differing in the degree of insulin resistance." (PMID 39684804, 2024). "Therefore, SKM dysfunction during BD exposure contributes to a disruption in lipid and protein homeostasis; moreover, it seems to promote the instauration of the insulin resistance process, since in SKM IRS-1 expression is decreased and hyperglycemia is appearing." (PMID 37676577, 2023). "Furthermore, PDB extracts promoted the expression of insulin receptor β (IRβ), insulin receptor substrate-1 (IRS-1), insulin receptor substrate-2 (IRS-2), and glucose transporter-4 (GLUT4) in the liver to enhance insulin sensitivity and reduce insulin resistance." (PMID 37849729, 2023). "Noteworthily, phosphorylated protein kinase B (p-Akt) is decreased and phosphorylated insulin receptor substrate 1 (p-IRS-1) Ser312 and phosphorylated c-Jun N-terminal protein kinase (p-JNK) are increased in skeletal muscle of patients with obesity, type 2 diabetes, and/or insulin resistance." (PMID 37298039, 2023). "However, elevated expression of p-IRS1 as a consequence of serine phosphorylation by JNK causes a decrease in PI3K and AKT expression, thus promoting the occurrence of insulin resistance and, ultimately, T2DM if not controlled." (PMID 37047241, 2023). "Insulin resistance has been found to accelerate Aβ formation in the vicinity of presynaptic neuronal cell membranes and has been correlated with activating the JNK-dependent signaling pathway with subsequent inhibitory phosphorylation of the insulin receptor substrate 1 (IRS-1) at S616." (PMID 37373216, 2023). "Therefore, the ability of berberine to protect experimental animals with type 2 diabetes mellitus from insulin resistance is due to the regulation of the expression of cAMP, PKA, PPM1B, PPARγ, LRP1, GLUT4, NF-B p65, JNK, IKKβ, IRS-1, IRS -2, PI3K, and AKT in the heart." (PMID 36770960, 2023). "In addition, because the expression of genes, such as insulin receptor substrate-1 (IRS1), protein kinase B (AKT), and GLUT4, tends to significantly reduce insulin resistance, gene regulation related to insulin metabolism can be used as an index to evaluate diabetes treatment." (PMID 37754257, 2023). "Moreover, SH and UA treatment upregulated the expression of IRS-1, AKT, and GLUT4, which are suppressed in insulin resistance, to a similar degree to metformin, and suppressed the expression of FoxO1, PEPCK involved in gluconeogenesis, and GSK-3β involved in glycogen metabolism." (PMID 37754257, 2023). "Importantly, inflammatory cytokine/PICR-signaling in neurons and the concomitant activation of the IRS-1-inactivating serine kinases JNK, IKKβ, and PKR lead to cerebral insulin resistance in AD which, in turn, promotes Tau hyperphosphorylation by enhancing the activity of the Tau kinase GSK-3β." (PMID 36117625, 2022). "The phosphorylation level of IRS1 Ser307 induced by JNK was significantly lower in JNK1 gene knockout mice fed a high fat diet (HFD), suggesting that it may have a protective role in the occurrence of impaired glucose tolerance and insulin resistance." (PMID 36589630, 2022). "Furthermore, peripheral insulin resistance might also be accompanied by central insulin resistance, IGF-1 resistance, and IRS-1 and IRS-2 dysfunction, presumably as a consequence of Aβ oligomers further contributing to cognitive decline." (PMID 35615716, 2022). "RNA-seq combined with a functional test indicated that the MCSEKO mice exhibited insulin resistance as evidenced by a decrease in intraperitoneal glucose tolerance test (IGTT) and insulin tolerance test (ITT) and down-regulated expression of insulin receptor substrate 1 (IRS1) and GLUT4." (PMID 36358588, 2022).
Insulin resistance (continued). "ANGPTL7 was found to play a critical role in inducing insulin resistance, which occurred through multiple mechanisms involving the down regulation of Insulin receptor (INSR), upregulation of suppressor of cytokine signaling 3 protein (SOCS3) to degrade insulin receptor substrate 1 (IRS1)." (PMID 36017324, 2022). "Insulin resistance has a prominent role in diabetes resistance, and was treated by curcumin through a reduction in the expression of SOCS3, in STAT3 signaling, by increasing the level of IRS-1 and Rac-1 and by suppression of phosphorylation of the ERK/JNK signaling pathway." (PMID 35807304, 2022). "Regarding the mechanism linking oxidative stress with insulin resistance, it has been described that the production of ROS promotes the activation of the serine/threonine kinases p38 MAPK, JNK and IKK, which are involved in the inhibitory phosphorylation of IRS-1." (PMID 33806797, 2021). "Likewise, levels of genes involved in glucose metabolism such as IRS-1, IRS-2, and GLUT-4 were reduced upon obesity or arthritis induction, either alone or combined, which may facilitate an insulin resistance state." (PMID 34721412, 2021). "As previously discussed, insulin resistance is a common hallmark of T2DM and AD, and it is mainly driven by the PI3K/Akt/mTOR signaling pathway; more precisely, neuronal insulin resistance driven mTOR hyperactivity inhibits IRS1 activity by negative feedback." (PMID 34069890, 2021). "Wu found that BSJPHX principle could significantly improve the clinical symptoms of TCM in patients with T2DOP, effectively reduce blood glucose and glycosylated hemoglobin, fasting insulin level and insulin resistance index, and improve BMD and serum IGF-1, IRS-1, IRS-2 levels." (PMID 33761702, 2021). "Consequently, miR-29s interacts with IRS1 and PI3K/Akt and contributes to insulin resistance." (PMID 34440850, 2021). "Additionally, the initiation of insulin resistance could decrease AMPK phosphorylation, further increase the expression of Srebp-1c, and eventually suppress the Irs-1-related insulin signaling pathway." (PMID 33936248, 2021). "Importantly, in line with previous studies, our protocol successfully induced insulin resistance in both adipose cell types as demonstrated by the 50% decrease in insulin-mediated phosphorylation of Akt and IRS-1, without changes in insulin potency." (PMID 32718202, 2020). "Recent studies have revealed that abnormal DAG content contributed to insulin resistance in different animal models due to the activation of conventional protein kinase C (PKC) (α, βI, βII, γ) and novel PKC (δ, ε, η, θ) isoforms that inhibited insulin receptor substrate 1 (IRS1) phosphorylation." (PMID 33171690, 2020). "TNF-α-induced phosphorylation of IRS-1 at Ser 307 leads to insulin resistance in liver cells, and a JNK inhibitor largely abolishes the phosphorylation of IRS-1 at Ser 307 and restores insulin resistance, indicating that JNK activity is involved in the mechanism of TNF-α-induced insulin resistance." (PMID 32842547, 2020). "However, IRS1 mSer307 knock-in mice display insulin resistance rather than increased insulin sensitivity, suggesting that IRS1 mSer307 is a positive regulatory site and is essential for normal insulin signaling." (PMID 31426549, 2019). "Although a link between the phosphorylation of neural IRS1 at mSer307, mSer612, and mSer632/635 and brain insulin resistance has been proposed, brain insulin resistance is not yet defined, and the phosphorylation of IRS1 at Ser sites emerges in insulin-dependent and insulin-independent manners." (PMID 31426549, 2019). "In addition, FJG partially corrected the abnormal protein levels of IRS-1, PI3K, Akt and Glut4 in ZDF (fa/fa) diabetic rats, suggesting a regulatory effect of FJG by alleviating insulin resistance in skeletal muscle through modulation of the PI3K signaling pathway." (PMID 31545909, 2019).
Insulin resistance (continued). "In conclusion, the present study evaluated the therapeutic effect of QDTS granules on DM kidney injury and insulin resistance, revealing that QDTS granules could restore the phosphorylation balance between the Ser and Tyr residues of IRS-1 via inhibiting the activation of MAPK pathway." (PMID 30050584, 2018). "These investigations suggest that reduced expression of KLF4 triggered by a high-fat diet in our mouse model (IR+/-IRS1+/-ApoE-/-) may mediate down-regulation of IRS2 and TSC2 expression thereby impairing insulin signaling in adipocytes and promoting insulin resistance." (PMID 30240435, 2018). "Indeed, miR-29a directly targets IRS1 3′UTR, thus repressing its expression; moreover, miR-29a is induced upon saturated fatty acid (palmitate) treatment, therefore contributing to the development of insulin resistance." (PMID 30469501, 2018). "Molecular mechanisms of the attenuation of insulin resistance include facilitated glucose transporter type-4 (GLUT-4) expression and glucose uptake, as well as increased insulin-stimulated phosphorylation of insulin receptor-β (IR-β) and insulin receptor substrate-1 (IRS-1)." (PMID 30336561, 2018). "Finally, tyrosine phosphorylation of insulin receptor substrate-1 (IRS1) was decreased and serine phosphorylation of the same substrate was increased in the liver of HFD-fed rats, indicating that these rats developed insulin resistance, a key feature of MS." (PMID 29367725, 2018). "Although our data do not allow us to rule out the contribution of other cellular serine kinases to the altered phosphorylation state of muscle IRS-1, it is highly plausible that JNK might serve as a candidate for the link between noise exposure and insulin resistance." (PMID 29433422, 2018). "To investigate whether mitochondrial function is regulated by insulin signaling, we analyzed muscle and liver of insulin receptor (IR)+/−-insulin receptor substrate-1 (IRS-1)+/− double heterozygous (IR-IRS1dh) mice, a well described model for insulin resistance." (PMID 28556799, 2017). "Chronic mTORC1 activation could further increase lipid storage in adipose tissues and develop insulin resistance via negative feedback regulation through the phosphorylation of IRS-1 at serine residues." (PMID 29077002, 2017). "Phospho-Ser307 in IRS-1 blocks the interaction between the IRS-1 PTB domain and insulin receptor, which might weaken the coupling between the two proteins and lead to insulin resistance." (PMID 28634451, 2017). "However, we did not observe any alteration in GLUT4 or p-IRS-1 expression, indicating its irrelevance in insulin resistance." (PMID 29020999, 2017). "A high dietary arginine level (2.70%) resulted in high plasma glucose, which may have contributed to a negative feedback mechanism that led to insulin resistance through the inhibition of IRS-1 and the upregulation of gluconeogenesis-related gene expression." (PMID 28801592, 2017). "Although IRS-1 serine phosphorylation by SFA is considered as an emerging detrimental factor in insulin sensitivity, a growing lines of evidence have suggested that the reduction of INSR expression also promotes the pathogenesis of insulin resistance and diabetes." (PMID 28036389, 2016). "Moreover, mice lacking both Irs1 and Irs2 failed to develop ‘selective insulin resistance' despite deletion of Irs2." (PMID 27708333, 2016). "Moreover, high glucose induced insulin resistance by decreasing the phosphorylation of GSK3β, triggering the ubiquitination and degradation of insulin receptor substrate (IRS1), which did not require insulin receptor signaling or PI3K/AKT activity." (PMID 25993471, 2015). "First, insulin resistance induced by excess insulin observed in this study occurred mainly in liver as evidenced by the increased level of serine-phosphorylated IRS1 and lack of Akt phosphorylation in response to acute insulin challenge in liver but not in muscle." (PMID 24741073, 2014).